MTOR (mechanistic target of rapamycin kinase)
Diseases named in the same sentence as MTOR in open-access papers (continued):
Sharing a sentence is not in itself a finding about the gene and the disease.
mantle cell lymphoma (53 papers, 2008 to 2025). Mantle cell lymphoma is a rare form of malignant non-Hodgkin lymphoma affecting B lymphocytes in the lymph nodes in a region called the ``mantle zone''. "Another study conducted by Rosich and colleagues on mantle cell lymphoma (MCL) revealed that autophagy was upregulated in MCL cells refractory to a combinatory treatment with everolimus (an mTOR inhibitor) and an Akt inhibitor." (PMID 37566004, 2023). "mTOR directly mediates Cyclin D1 downregulation through glycogen synthase kinase (GSK)-3b in mantle cell lymphoma (MCL)." (PMID 33489922, 2020). "Previously, edelfosine has been shown to inhibit PI3K/Akt survival pathway by displacing Akt as well as key regulatory kinases p-PDK1 (phosphatidylinositol-dependent protein kinase 1), PI3K and mTOR from lipid rafts in mantle cell lymphoma cells." (PMID 30399177, 2018). "Upregulation of miR-92a was shown to activate PI3K/AKT/mTOR pathway and inhibit cell apoptosis induced by chemotherapy in mantle cell lymphoma (MCL) cells." (PMID 30305865, 2018). "Recently, a quinoxaline analog 13-197, a NF-kB and mTOR dual small molecule inhibitor, has been described to inhibit NF-kB and mTOR pathways by targeting the upstream central kinase IKKβ in pancreatic tumor and mantle cell lymphoma in vitro and in vivo." (PMID 26934655, 2016). "For example, vorinostat suppresses cyclin D1 in mantle cell lymphoma cells by blocking the translation of cyclin D1 via inhibiting the phosphatidylinositol 3-kinase (PI3K)/Akt/mTOR/eIF4E-BP pathway most likely by PI3K inhibition." (PMID 26681199, 2015). "Temsirolimus, an inhibitor of MTOR, induces autophagy and cell cycle arrest to result in proliferation inhibition of mantle cell lymphoma." (PMID 25375091, 2014). "Analogs of the allosteric mTOR inhibitor rapamycin are approved for mantle cell lymphoma but have limited efficacy in other blood cancers." (PMID 24586420, 2014). "The addition of CQ increased PI3K/AKT/mTOR inhibitor-induced cell death in models of malignant peripheral nerve sheath tumors and in mantle cell lymphoma cells that were resistant to Akt/mTOR targeting, resulting in induction of cell death via apoptosis." (PMID 23383069, 2013). "The majority (>50%) of mantle cell lymphoma, Burkitt lymphoma, diffuse large B-cell lymphoma, anaplastic large-cell lymphoma and Hodgkin-lymphoma cases showed higher mTOR activity compared to normal lymphoid tissues." (PMID 23693095, 2013). "Inhibition of mTOR by temsirolimus as a novel mechanistic strategy for the treatment of other advanced malignancies, including mantle cell lymphoma, is actively being studied in several clinical trials." (PMID 18458675, 2008). "Moreover, the expression of GAS5 is related to mTOR signaling pathway, which makes it a mediator of cytotoxic and cytostatic effects of rapalogues in mantle cell lymphomas." (PMID 35054253, 2021). "Dual inhibition of PI3K and mTOR with BEZ235 could overcome acquired resistance to bortezomib in mantle cell lymphoma cells and suppress the activated Akt/mTOR pathway." (PMID 24252210, 2013). "Phosphatidylinositol-3-kinase (PI3K)/Akt/mammalian target of rapamycin (mTOR) pathway activation contributes to mantle cell lymphoma (MCL) pathogenesis and drug resistance." (PMID 25216518, 2014). "mTOR has indeed been proven an important element in tumorigenesis in mantle cell lymphoma (MCL): its role was confirmed in MCL cell proliferation, mainly by influencing cyclin D1 expression." (PMID 23693095, 2013). "This review is mainly focused on the PI3K/v-akt/mTOR pathway-related oncogenic mechanisms in B cell NHLs with an emphasis on common B cell lymphoma types [diffuse large B cell lymphoma (DLBCL) and mantle cell lymphoma (MCL)]." (PMID 37762410, 2023). "mTOR signaling plays a pivotal role in the aberrant OXHPHOS and glycolysis in B-cell derived lymphoma, including DLBCL, follicular lymphoma (FL), mantle cell lymphoma (MCL)." (PMID 35761419, 2022).
mantle cell lymphoma (continued). "Glycolysis inhibition through mTOR targeting has also been observed in mantle cell lymphoma (MCL)." (PMID 32053876, 2020). "For example, temsirolimus could significantly prolong progression-free survival of mantle cell lymphoma (MCL) patients by inhibiting the mechanistic target of rapamycin (mTOR) protein, a post-translational autophagy regulator." (PMID 30400235, 2018). "In mantle cell lymphoma (MCL), AICAR-mediated stimulation of AMPK activity dampened phosphorylation of critical downstream effectors of mTOR signaling, such as 4E-BP1 and ribosomal protein S6, leading to cell growth inhibition." (PMID 30274374, 2018). "An investigation on mantle cell lymphoma (MCL) cells showed that compared with everolimus (an mTOR inhibitor) or NVP-BKM120 (a PI3K inhibitor), BEZ235 could be more potent in suppressing the PI3K/Akt/mTOR pathway." (PMID 37046703, 2023). "For example, in mantle cell lymphoma (MCL), PI3K and AKT, but not mammalian target of rapamycin (mTOR), inhibitors have been demonstrated to be able to cause significant reduction in leukaemic cell viability, which is again associated with FOXO3 nuclear translocation and activation." (PMID 29180117, 2018).
influenza (52 papers, 2013 to 2026). An acute viral infection of the respiratory tract, occurring in isolated cases, in epidemics, or in pandemics; it is caused by serologically different strains of viruses (influenzaviruses) designated A, B, and C, has a 3-day incubation period, and usually lasts for 3 to 10 days. "The mTOR-associated pathway involving AMP-activated protein kinase (AMPK) is a key mechanism underlying influenza-induced metabolic reprogramming in TLR 7/9-activated-plasmacytoid dendritic cells (pDCs)." (PMID 41511331, 2025). "mTOR has been already associated with the development of influenza by promoting influenza virus replication." (PMID 32883368, 2020). "Since both pharmacological promotion of autophagy by Rapamycin and influenza upregulate autophagic activity by inhibiting mechanistic target of rapamycin (mTOR), these results suggest a relationship between influenza-induced autophagy and loss of pluripotency." (PMID 31000695, 2019). "Our findings suggest that targeting cholesterol synthesis and/or mTOR/Akt signaling may hold promise for reducing susceptibility to influenza infection in patients with advanced lung disease and hypercapnia." (PMID 40362373, 2025). "Therapeutic treatment of aged females with either estradiol or a selective estrogen receptor α modulator increased mTOR signaling and improved vaccine-induced antibody responses, thereby eliminating the effects of aging on influenza immunity." (PMID 41744685, 2026). "The inhibition of the mTOR pathway was evaluated by measuring the immune response to influenza vaccination, with a particular focus on T cell activation and proliferation." (PMID 41159033, 2025). "The avirulent virus-induced mTOR pathway more noticeably than the virulent virus indicates that this pathway was differentially regulated in response to influenza infection." (PMID 36059479, 2022). "Pilot studies of a short course of pharmacological mTOR inhibition in older human volunteers report increased responses to influenza vaccines (suggesting decreased immune senescence) and a reduction in self-reported viral respiratory infections." (PMID 36103894, 2022). "Inhibition of the mTOR pathway significantly enhances the immune response to vaccination and by doing so reduces influenza infections." (PMID 36284901, 2021). "In this study, autophagy benefited the replication of influenza through the Akt/TSC2/mTOR signaling pathways." (PMID 33461581, 2021). "A later study by the same group has shown that low doses of mTOR inhibitors result not only in better responses to influenza vaccination but in an overall decrease in the incidence of infectious disease in the elderly." (PMID 31632966, 2019). "Later studies performed in old humans confirmed that inhibition of mTOR resulted in clearly enhanced responses to influenza vaccine and also in reduced expression of exhaustion markers such a PD-1." (PMID 31632966, 2019). "The higher viral load on day 10 post-infection suggests a need for mTOR signaling early in the course of influenza infection." (PMID 28693498, 2017). "Taken together, these data demonstrate that the role of mTOR in modulating influenza infection deserves further studies." (PMID 28693498, 2017). "Prior studies have reported that combining an mTOR inhibitor with hormones and antiviral drugs improves clinical outcomes, such as hypoxemia and multi-organ failure, in the treatment of Middle East respiratory syndrome and severe influenza." (PMID 38956624, 2024). "Human studies are being conducted to investigate the effects of mTOR inhibition on aging, with a recent study showing that the mTOR inhibitor RAD001 increased antibody titers to influenza vaccination and lowered programmed death protein (PD) 1 expression on CD4+ and CD8+ T cells." (PMID 37958564, 2023).
influenza (continued). "Herein, metformin administration of 6 weeks prior to vaccination was used on the basis of several prior studies including a murine study that demonstrated a 6-week course of an mTOR inhibitor that increased naïve lymphocytes, influenza vaccination responses, and extended life span." (PMID 35821804, 2022). "Interestingly, phenformin, an antidiabetic drug and an mTOR inhibitor, has been postulated as an inhaled drug candidate against influenza and coronavirus infections." (PMID 35025963, 2022). "Finally as well, it is known that metformin blocks the mTOR pathway, while mTOR plays a crucial part in the pathogenesis of influenza and Middle East respiratory syndrome coronavirus infection." (PMID 33807522, 2021). "The reduction in protein levels at a late stage of infection could be attributed to post-transcriptional regulation of mTOR by miRNA, which have been reported to be altered during influenza infection." (PMID 32326380, 2020). "Furthermore, oral administration of an mTOR inhibitor (Rapamycin) prior to influenza vaccination of older adults resulted in increased antibody titers against all three strains of a trivalent influenza vaccine by more than 20% in individuals aged above 65 years." (PMID 33178213, 2020). "Thus, the effects of mTOR inhibitors on influenza infection deserve further studies." (PMID 28693498, 2017). "Innate trained immunity has been observed in human monocytes and macrophages following influenza infection, characterized by a shift from OXPHOS to aerobic glycolysis, and mTOR/AKT-driven metabolic reprogramming." (PMID 41511331, 2025). "While mTOR is involved in the TLR9-induced type I interferon signaling pathway, and stimuli such as the TLR7-agonist gardiquimod or Influenza induce early glycolysis in pDCs, the effect of TLR4-ligands on the metabolism of pDCs is not well studied." (PMID 36059475, 2022). "In addition, previous researches have demonstrated that pneumovax is effective in preventing both influenza (in 70–80% of people) and pneumococcal infection (in 60–70% of people), thus it might be a potential effective therapy for preventing mTOR inhibitors related pneumovax in cancer patients." (PMID 23785409, 2013). "Considering the anti-cancer findings, the metabolic reprogramming observed in alveolar macrophages (AMs) post-influenza infection, as depicted by elevated glycolysis, PI3K–Akt, HIF-1, and mTOR signalling, underscores the therapeutic promise of leveraging trained immunity against cancer." (PMID 39060761, 2024). "Notably, a recent study on the mTOR inhibitor RAD001 offers promising insights, showing improved immune function in elderly humans, as evidenced by enhanced responses to influenza vaccination." (PMID 38797976, 2024). "A low dose combination of mTOR inhibitors RAD001 and BEZ235 enhanced antibody responses to influenza vaccination and reduces respiratory infection incidence in the elderly, which reveals a potential role of the mTOR signaling pathway in vaccination efficiency in the elderly." (PMID 33808998, 2021). "In this respect, mTOR mainly influenced bacterial and fungal induction of cytokines, whereas viral (influenza) stimulated cytokines were not impacted." (PMID 32999407, 2020). "A recent report indicated that influenza virus induces metabolic phosphatidylinositide 3-kinase (PI3K)/mTOR changes; however, the PI3K/mTOR inhibitor BEZ235 restores PI3K/mTOR pathway homeostasis and significantly reduces viral titer to alleviate lethal influenza infection." (PMID 30422993, 2018).
small cell lung carcinoma (52 papers, 2010 to 2025). Small cell lung cancer (SCLC) is a highly aggressive malignant neoplasm, accounting for 10-15% of lung cancer cases, characterized byrapid growth, and early metastasis. "The findings revealed a positive correlation with the ATO + APA groups and signals associated with cancer, organ system cancer, lung small cell carcinoma, the mTOR signaling pathway, apoptosis, and response to endoplasmic reticulum stress." (PMID 39223679, 2024). "Small-cell lung cancer (SCLC) caused by MYC preferentially stimulates the mTOR and polyamine synthesis pathways, both of which are controlled by arginine." (PMID 38002277, 2023). "It has been reported that small cell lung cancer may be associated with chemotherapy resistance due to a phenotypic transition from suspension to an adhesion growth pattern caused by the activation of the PI3K/Akt/mTOR pathway." (PMID 36243681, 2022). "Genetic modification of the PI3K/AKT/mTOR pathway have been identified as a potential therapeutic strategy for small-cell lung cancer (SCLC)." (PMID 39858036, 2025). "On the other hand, diagnosing LCNEC can be challenging due to its histological similarities with non-small-cell lung cancer (NSCLC) and, in some cases, small-cell lung cancer (SCLC) (as evidenced by the PI3K/Akt/mTOR pathway and other gene alterations)." (PMID 39201255, 2024). "Unbiased high-throughput drug combination screens reveal that PI3K-AKT-mTOR pathway inhibitors exert synergistic anticancer effects with BRD4 inhibitors against small cell lung cancer cells, and mTOR inhibitors exhibit the best synergy." (PMID 38135679, 2023). "mTOR pathway has been linked to multiple smoking-related cancers including: laryngeal SCC, small cell lung carcinoma and transitional cell bladder carcinoma." (PMID 30308005, 2018). "The phosphoinositide-3 kinase (PI3K)/Akt/mammalian target of rapamycin (mTOR) signaling pathway plays an important role in cancer progression and treatment, including that of small cell lung cancer (SCLC), a disease with traditionally poor prognosis." (PMID 28280736, 2017). "A variety of novel therapeutics targeting receptor tyrosine kinases, mammalian target of rapamycin (mTOR), angiogenesis, cell cycle, epigenetics, and immunotherapy have been tested, largely in small cell lung cancer, with limited success." (PMID 26444865, 2015). "EGFR, p-AKT, p-ERK, p-mTOR and p-p70s6K protein expressions were studied by immunohistochemistry in 107 small cell lung carcinomas and correlated with clinicopathological parameters." (PMID 20683448, 2010). "In multiple patient-derived xenograft models of small cell lung cancer, combination therapy with the mTOR inhibitor Everolimus and the BRD4 inhibitor NHWD870 synergistically induce cancer cell apoptosis and blocks tumor progression without significantly increasing toxicity to normal tissues in mice." (PMID 38135679, 2023). "A previous study has shown that upregulation of receptor tyrosine kinase AXL or downstream targets of AXL and PI3K/mTOR pathways were the strongest markers of resistance to Adavosertib identified in the proteome of a resistant small cell lung carcinoma (SCLC) cell line." (PMID 38020882, 2023). "Naringin treatment also suppressed cell viability and proliferation, and promoted apoptosis in human small cell lung cancer cells (H69AR) by regulation of miR-126/Akt/mTOR/PI3K pathway via miR-126 overexpression and suppression of VCAM-1, p-Akt, PI3K, NF-κB, and p-mTOR pathways." (PMID 33854437, 2021). "Highly miRNA-targeted pathways include mTOR (nine miRNAs), MAPK (eight), focal adhesion, ubiquitin-mediated proteolysis, and small-cell lung cancer (seven each), plus several cancer and signaling pathways (six each)." (PMID 40806181, 2025). "SQSTM1 showed enrichment in small cell lung cancer (ES = 0.598, NES = 1.50, p = 0.0021), phosphatidylinositol signaling system (ES = 0.607, NES = 1.39, p = 0.0139), mTOR signaling pathway (ES = 0.617, NES = 1.37, p = 0.0172), among others." (PMID 41105646, 2025).
small cell lung carcinoma (continued). "For example, palbociclib in combination with mTOR inhibitors (i.e. rapamycin and everolimus) or the dual mTOR/phosphatidylinositol 3-kinase (PI3K) inhibitor PF04691502 enhanced senescence in bothin vitro and in vivonon-small cell lung cancer models." (PMID 41388212, 2025). "Inhibition of the PI3K/AKT/mTOR pathway promotes G6PD protein degradation, reducing radiotherapy resistance in small cell lung cancer." (PMID 40533802, 2025). "In small cell lung cancer research, inhibition of the PI3K/AKT/mTOR pathway overrided chemotherapy resistance mediated by ECM." (PMID 39066845, 2024). "Subsequent functional enrichment analyses showed that these genes were enriched in lung disease, lung small cell cancer, the PI3K-Akt-mTOR pathway, and in epithelial-mesenchymal transition processes." (PMID 35742854, 2022). "The purpose of this study is to investigate the effects of Apatinib alone or Apatinib combined with mammalian target of rapamycin (mTOR) inhibitor, CCI-779, on small cell lung cancer cell line NCI-H446 in vitro." (PMID 32209188, 2020). "Consistent with this, initial clinical trials of mTOR inhibitors suggest that they are effective in NSCLC and small cell lung carcinoma therapy." (PMID 25360163, 2014). "After combined with mTOR inhibitor CCI-779, low concentration of Apatinib could inhibit the proliferation and migration of NCI-H446 small cell lung cancer cells and induce apoptosis." (PMID 32209188, 2020). "In addition, tumor pathways were also significantly enriched, including small cell lung cancer, NOTCH, and mTOR signaling pathways which were often altered in cancer tissues." (PMID 28567416, 2017). "However, the mechanism of chemotherapy resistance in small cell lung cancer, which is characterized by many abnormalities in signaling pathways involving PIK3CA (PI3K/Protein kinase B [Akt]/the mammalian target of rapamycin [mTOR] pathway), may be informative." (PMID 36243681, 2022). "The additional mechanisms could include changes in tumor histology with tumor cells displaying features of small-cell lung cancer (SCLC) or epithelial mesenchymal transition (EMT), or alterations in other novel genes involved in the MAP kinase and mTOR pathway." (PMID 34385540, 2021).